SGK1 (serum/glucocorticoid regulated kinase 1)
Diseases named in the same sentence as SGK1 in open-access papers (continued):
Sharing a sentence is not in itself a finding about the gene and the disease.
periodontitis (1 paper, 2022). An acute or chronic inflammatory process that affects the tissues that surround and support the teeth. "Recent studies found that SGK1 was associated to many other diseases, such as hypertension, diabetes, recurrent pregnancy loss, multiple sclerosis, and periodontitis." (PMID 35588785, 2022). "Future studies examining the expression of SGK1, TRAF3, and c-Jun and their relevance to the predisposition to periodontitis will unravel the potential therapeutic significance of these protein kinases." (PMID 35588785, 2022). "Therefore, further investigation on P. gingivalis infection–mediated global alteration of E3s will warrant the critical regulatory function of SGK1 in periodontal inflammation and open a new avenue to elucidate the pathogenesis of periodontitis." (PMID 35588785, 2022). "As overwhelming neutrophil and macrophage accumulation are critical to the development of periodontitis and our in vitro data showed SGK1 inhibition enhances production of MIP-2, we next examined whether SGK1 inhibition affects inflammatory cell infiltration by staining tissue sections with H&E." (PMID 35588785, 2022).
pheochromocytoma (1 paper, 2023). "Therefore, to further explore the possible role of SGK1 in regulating nerve function, this study uses SGK1 inhibitors to inhibit the expression of SGK1 in rat adrenal pheochromocytoma-derived PC12 cells, which is a commonly used in vitro research platform for neuroscience research." (PMID 37371111, 2023).
pneumonia (1 paper, 2022). An acute, acute and chronic, or chronic inflammation focally or diffusely affecting the lung parenchyma, caused by an infection in one or both of the lungs (by bacteria, viruses, fungi, or mycoplasma.). "We also investigated the involvement of SGK1 in N protein-induced pneumonia in vivo." (PMID 35896532, 2022).
pulmonary edema (1 paper, 2020). Accumulation of fluid in the lung tissues causing disturbance of the gas exchange that may lead to respiratory failure. "In the study of pulmonary edema, it is speculated that miR-7-5p can affect the activity of the mTORC2/SGK-1 pathway to regulate the expression of sodium channels, which affects the formation of pulmonary edema." (PMID 33392188, 2020).
rhabdomyosarcoma (1 paper, 2020). A rare aggressive malignant mesenchymal neoplasm arising from skeletal muscle. "In doxorubicin (DOX)-treated rhabdomyosarcoma, SGK1 was found to often be upregulated and led to a poor prognosis." (PMID 33542904, 2020).
Sjögren’s syndrome (1 paper, 2025). "In this retrospective study of subjects with xerostomia (and suspected of having Sjögren’s syndrome), we observed increased expressions of SGK-1 and α-ENaC, raising the question of their utility as diagnostic biomarkers for this condition." (PMID 40837620, 2025).
skin cancer (1 paper, 2024).
tuberculosis (1 paper, 2021). A chronic, recurrent infection caused by the bacterium Mycobacterium tuberculosis. "Nevertheless, ChEMBL2109743, while known to inhibit human serum and glucocorticoid-regulated kinase 1 (SGK-1), has been observed to have low cellular toxicity in the GSK tuberculosis screening." (PMID 34012976, 2021).
ventricular tachycardia (1 paper, 2023). A disorder characterized by an electrocardiographic finding of three or more consecutive complexes of ventricular origin with a rate greater than a certain threshold (100 or 120 beats per minute are commonly used). "Moreover, mice with constitutively active SGK1 have a prolonged QTc, spontaneous ventricular tachycardia, and SCD." (PMID 37124559, 2023).
xerostomia (1 paper, 2025). Dryness of the mouth resulting from reduced salivary secretion. "Collectively, the data suggest a difference between the active form of the kinase and α-ENaC in minor salivary glands in xerostomia and that higher SGK-1 and α-ENaC may serve as diagnostic markers for this condition." (PMID 40837620, 2025). "These novel observations suggest a difference between α-ENaC and the active form of SGK-1 in xerostomia." (PMID 40837620, 2025). "In conclusion, despite a relatively small sample size, the present study showed increased expression of SGK-1 and α-ENaC in the ductal cells of the minor salivary glands of subjects reporting xerostomia compared to control subjects." (PMID 40837620, 2025). "We tested the hypothesis that expressions of SGK-1 and ENaC are affected in the lower lip minor salivary gland specimens from patients reporting xerostomia." (PMID 40837620, 2025). "We tested the hypothesis that lower lip minor salivary gland expressions of SGK-1 and ENaC are affected in subjects reporting xerostomia." (PMID 40837620, 2025). "The present study showed increased expression of α-ENaC and SGK-1, but not pSGK-1, in minor salivary glands of subjects reporting xerostomia compared to those of control subjects with presentation of mucocele." (PMID 40837620, 2025). "We found increased expression of SGK-1, but not pSGK-1, in the minor salivary glands of subjects reporting xerostomia than in control subjects." (PMID 40837620, 2025).
Yersinia infection (1 paper, 2013). "The small molecule CKI-7 was used to validate the role of SGK1 (serum and glucocorticoid-inducible kinase 1) on NF-κB-regulated gene expression in response to Yersinia infection." (PMID 24206648, 2013).
cancer (95 papers, 2010 to 2026). A tumor composed of atypical neoplastic, often pleomorphic cells that invade other tissues. "SGK1 was a good choice because its abnormal expression has significant cellular effects and is strongly linked to human cancer." (PMID 40613901, 2025). "High SGK1 expression has been reported in many types of cancer cells, and it has been implicated in promoting cell survival and resistance to chemotherapeutic agents." (PMID 37343701, 2023). "Several studies on SGK1 revealed that its expression is elevated in a multitude of cancers and was found to be associated with cancer growth, survival, and metastasis." (PMID 35106936, 2022). "This study employs a systematic computational approach based on various biophysical algorithms to study the impact of mutations on SGK1 structure and function for understanding their association with multiple diseases, such as cancer and neurodegeneration." (PMID 34805284, 2021). "A myriad of physiological roles is attributed to GILZ and SGK-1, and their dysregulations are implicated in diverse pathological conditions such as cancer." (PMID 35048019, 2021). "SGK1 expression is elevated in several tumors, including PCa, and is also associated with tumor growth, survival, cell cycle disorder, cancer stem cells, metastasis and chemoresistance." (PMID 34868959, 2021). "This study provides meaningful insights into SGK1 dysfunction upon mutation, leading to disease progression, including cancer, and neurodegeneration." (PMID 34805284, 2021). "Although the key roles of SGK1 in cancer metabolism have been identified, the underlying mechanisms of SGK1 involvement in metabolism regulation need to be further investigated in cancer." (PMID 33542904, 2020). "Due to the fact that SGK1 has been associated with drug resistance in several types of cancer, targeting of SGK1 in combination with ICIs can provide a potential synergy because of both tumor cell-intrinsic and -extrinsic effects." (PMID 33266470, 2020). "This review highlights the scientific achievements of human cancer research on SGK1, outlines the advances, and challenges in application of SGK1 as a diagnostic and prognostic tool in cancer, and discusses its biological function and clinical insights." (PMID 33542904, 2020). "Our approach will be proved useful in the designing of drugs while using natural leads as potent inhibitors of SGK1 for the therapeutic management of cancer and other associated diseases." (PMID 32070031, 2020). "We found that the Sgk1 status in carcinoma cells was not only significantly associated with shorter OS and DFS but also with more advanced pT, pN, and lymphatic vessel invasion in ESCC patients." (PMID 32106831, 2020). "A high NDRG1 status in carcinoma cells in pre-NAC biopsy specimens was significantly associated with lower NAC effects, and a high GR and Sgk1 status in carcinoma cells tended to be associated with lower NAC effect." (PMID 32106831, 2020). "Accordingly, tumor cell survival by an SGK-1 mediated mechanism has been implicated for IL-6-, IL-2, angiotensin II-, and androgen-receptor dependent cancer cells." (PMID 25485633, 2014). "Because of quite an impressive involvement of SGK1 in the development and growth of various tumors, it would be logical to predict, that this kinase is a potential diagnostic, prognostic, or predictive biomarker in cancers." (PMID 35625991, 2022). "In conclusion, the identified compound ZINC00319000 might be further exploited as a scaffold to develop promising inhibitors of SGK1 for the therapeutic management of associated diseases, including cancer." (PMID 32070031, 2020). "In addition, low SGK1 expression in untreated tumors was associated with an increased risk of cancer recurrence (adjusted log-rank test P = 0.077), with 5-year progression-free survival of 47.8% versus 72.6% (P = 0.034)." (PMID 33542904, 2020).
cancer (continued). "However, their data further suggested that relatively low expression of SGK1 is associated with higher tumor grade and increased cancer recurrence (adjusted log-rank test P = 0.077) and is a potential indicator of aberrant AR signaling in these tumors." (PMID 33542904, 2020). "Therefore, understanding the mechanisms underlying SGK1 activation and its role in promoting cancer cell survival and resistance may provide valuable insights for developing effective cancer therapies." (PMID 37343701, 2023). "Furthermore, low sodium levels could stabilize or enhance via hypotonic stress the transcription of the glucocorticoid-induced protein kinase 1 (SGK1), which has been recently linked to cancer cell metastatization." (PMID 31506579, 2019). "Interestingly, SGK1 inhibition abrogated the rescue effect of oleic acid in serum-deprived hypoxic cancer cells and this effect was associated with a reduction in FA uptake particularly in anoxia-tolerant cancer cells exposed to severe hypoxia." (PMID 27251632, 2016). "Therefore the future development of SGK1 mimetics could represent a novel class of molecules used to prevent muscle wasting in clinical setting such as cancer and after appetite loss as well as to attenuate the effects of sacropenia." (PMID 25807490, 2015). "High levels of SGK1 expression have been observed in many cancers, which are attributed to various factors, such as promoter methylation and aberrant splicing of mRNA." (PMID 37343701, 2023). "The serum- and glucocorticoid-induced kinase 1 (SGK1) promotes cell survival under stress conditions and facilitates the emergence of drug resistance in cancer." (PMID 37343701, 2023). "Since pSGK-1 is the active and the pro-survival form of SGK-1, its reduction in is suggestive of an adaptive mechanism to curtail tumor growth, an aspect of translational relevance in relation to use of SGK-1 inhibitors as therapeutic options in cancer." (PMID 37954869, 2023). "For example, GR driven SGK1, seems to induce a cancer stem-like phenotype, suggesting a possible impact on tumor pathogenesis, in association with heightened TDO/kynurenine/AhR mediated rise in the NAS/melatonin ratio in microenvironment cells." (PMID 37970210, 2023). "More research is needed to understand the specific role of SGK1 in various cellular processes and its potential as a therapeutic target for diseases like cancer." (PMID 37343701, 2023). "SGK1 has also been studied in relation to inflammation in helper T cells, pro-tumorigenesis in some cancer types, and as a prognostic factor." (PMID 37371111, 2023). "Overall, the candidate gene set was significantly enriched for known cancer census genes (e.g. SGK1, MECOM, PRKCB) and known transcription co/factors (e.g. CACNA2D3, BMP4)." (PMID 36624125, 2023). "A commercial human SGK1 anti-pS422 antibody was employed to detect HM phosphorylation of SGK1 in cell lysate of 293T and the indicated human cancer cell lines." (PMID 37343701, 2023). "The expression of SGK1 is under transcriptional and post‐translational regulations that are frequently altered in cancer and immune disorders." (PMID 35393773, 2022). "It is noteworthy that the implication of PDCD5/HDAC3/miR-195-5p/SGK1 axis in RCC has been rarely studied through their respective interaction which has been briefly mentioned in other cancers." (PMID 36266728, 2022). "This chapter focuses on major aspects of SGK1 involvement in cancer, its use as biomarker as well as potential therapeutic target." (PMID 35625991, 2022). "Recently, SGK1 has also been demonstrated to be involved in cancer as the main effector of the aberrant deregulation of SRC kinase signaling, a major driver of cancer development and resistance to therapy." (PMID 35883458, 2022). "We next screened tumour derived cells as high SGK1 expression has been reported in numerous cancer types." (PMID 35393773, 2022).
cancer (continued). "SGK1 is essential for the proliferation of cancer cells that rely on PI3K activation, and SGK1 deficiency reduces the proliferation and viability of cancer cells in various malignant cancers." (PMID 35106936, 2022). "SGK1 plays multiple roles in the tumor, such as tumorigenesis, cancer cell proliferation, apoptosis, invasive, and migration." (PMID 35711939, 2022). "Aberrations of AGC kinases, including mutations/amplifications of AKT, PKC, S6K1, and serum/glucocorticoid-regulated kinase 1 (SGK1), often occur under various pathological conditions, especially in cancer development and progression." (PMID 35879299, 2022). "In the present review, we focus on providing current and in-depth evidence regarding the function of SGK1 in sodium transport, cancer progression, and immune modulation." (PMID 36457711, 2022). "Given the pleiotropic role of SGK-1 in cancer biology, it has attracted much attention as a novel therapeutic target." (PMID 35048019, 2021). "The transcription of three genes associated with cancer, CDKN1A, SGK1 and CHKA, were measured using qRT-PCR." (PMID 32910239, 2021). "Next, WB analysis showed that among these 4 candidate cancer genes, only SGK1 was highly expressed in C4-2-EnzR cells." (PMID 34868959, 2021). "SGK1 is a positive regulator of cancer progression, proliferation, and migration, and, thus, can be utilized as an attractive drug target for the development of anticancer therapeutics." (PMID 32070031, 2020). "All these studies indicate that SGK1 plays a key role in tumor chemotherapy resistance and is a promising therapeutic target of cancer." (PMID 33542904, 2020). "Various transcriptional factors, including activators and repressors, have been found to be involved in the regulation of SGK1 expression in human cancer, which has been reviewed above in this study." (PMID 33542904, 2020). "In the present study, an in-silico analysis using structure-based vHTS of the ZINC database of natural products against SGK1 was carried out to identify its potent inhibitors, which can further be used in the development of potential drugs against cancer." (PMID 32070031, 2020). "Taken together, this evidence highlights the crucial role of SGK1 in tumorigenesis and cancer progression, revealing why it has emerged as a potential target for cancer therapy." (PMID 33542904, 2020). "SGK1 not only has great potential in indicating the clinical features of human cancer but also plays an important role in predicting the progression and prognosis of cancer patients." (PMID 33542904, 2020). "Most importantly, SGK1 is overexpressed in cancer and consistent evidence suggests that SGK1 can be a prognostic factor and a potential therapeutic target for the treatment of NSCLC." (PMID 33266470, 2020). "The following section will detail the findings related to the functional roles of SGK1 in diverse human cancers." (PMID 33542904, 2020). "SGK1 appears to promote oncogenic signaling aimed at preserving the survival and fitness of cancer cells." (PMID 33266470, 2020). "The role of SGK1 in human cancer has been explored in numerous clinical, translational, and basic studies." (PMID 33542904, 2020). "A growing number of investigations suggest that SGK1 is a potential predictor of tumor type, tumor grade and lymph node metastasis in multiple human cancer types." (PMID 33542904, 2020). "These evidence suggests the significance of SGK1 in terms of its correlation with cancer staging, differentiation, and metastasis." (PMID 33542904, 2020). "Mechanistically, the expression of SGK1 can be regulated via both transcriptional factors and epigenetic factor-induced mechanisms in cancer cells." (PMID 33542904, 2020). "Several reports have indicated that SGK1 exhibits an oncogenic role in the initiation of human cancer." (PMID 33542904, 2020). "Aberrant expression of SGK1 has profound cellular consequences and is closely correlated with human cancer." (PMID 33542904, 2020).